CD4 (CD4 molecule)
Diseases named in the same sentence as CD4 in open-access papers (continued):
Sharing a sentence is not in itself a finding about the gene and the disease.
tumor (continued). "When Rag1−/− mice are challenged with tumors and then receive adoptively transferred wild-type CD4+ and CD8+ T cells, these T cells are able to mediate an anti-tumor response and keep tumor growth in check." (PMID 24151492, 2013). "Observationsshow that the presence of T-helper (CD4+) and cytolytic(CD8+) cells are required for tumor rejectionin vitro." (PMID 23700562, 2013). "It has also been shown that tumor-related factors activate CD4+CD25high Treg cells (as indicated by increasing their expression of CD69), expand CD4+CD25high Treg cells and enhance their suppressive capacity." (PMID 23378947, 2013). "Immunohistochemical examination revealed that the tumour cells expressed T-cell receptor (TCR)-βF1, CD3, CD4, CD25, cytotoxic-related protein TIA1 and granzyme-B, but were negative for CD8, Foxp3, CD20, CD30 and CD56." (PMID 23302373, 2013). "We have shown that rAAV-SLC was more effective in generating systemic antitumor responses and was accompanied by extensive CD4+, CD8+T cells, as well as CD11c+DCs infiltrating into the tumor sites." (PMID 24078089, 2013). "CD4+ and CD8+ T cells are predominantly present in the stroma either dispersed or in aggregates, mainly at the periphery of the tumor." (PMID 23950747, 2013). "One important function of CD4+ T cells is their help for CD8+ T cell and antibody responses against virus or tumor antigens." (PMID 22890822, 2013). "The frequencies of PD-1+ cells were also higher in CD4+ T cells in blood and both CD4+ and CD8+ T cells in tumor-bearing LN from BCBL than mesenteric LN from BLV+ and BVL- cattle." (PMID 23876077, 2013). "In 10 patients with available matched tumor specimen and peripheral blood samples, significantly higher percentage of CD4 + FOXP3+ T-regulatory cells and lower ratio of CD8+/CD4 + FOXP3+ in the tumor compared with blood were reported." (PMID 24499550, 2013). "First, when either CD4+ or CD8+ cell populations are eliminated, the IL-12-producing cells lose their ability to protect the mice from tumour development." (PMID 24251770, 2013). "The important role of tumor-specific cytotoxic CD8+ T cells is well defined in the immune control of the tumors, but the role of effector CD4+ T cells is poorly understood." (PMID 22890822, 2013). "We then studied with in vivo cell-depletion experiments the role of CD8+ and CD4+ T cells in the tumor rejection phase and found the importance of CD8+ and of both CD4+ and CD8+ T lymphocyte subsets in the eradication of K7M2 and WEHI-164 tumors, respectively." (PMID 24156020, 2013). "We therefore tested this in the EG-7 tumour model, in which there is expression of the OVA antigen recognised by CD4 and CD8 T cells available from OTII and OTI TCR transgenic mice, respectively." (PMID 23717511, 2013). "CD3+CD4+ T lymphocytes and CD3+CD8+ T lymphocytes populations were higher in tumor+MF group than those in tumor group (n = 9, p<0.05)." (PMID 24278103, 2013). "MB49 expresses well-characterized H2Db-restricted CD4+ and CD8+ epitopes derived from the HY male antigenic complex, and tumor-induced expansion of HY-specific T cells can be measured during tumor progression." (PMID 23554941, 2013). "CD4+ CD25+ Foxp3+ Tregs play a crucial role in maintaining a suppressive environment and inhibiting anti-tumor responses." (PMID 24339825, 2013). "In order to focus on CD8+ T cells and eliminate the contribution of CD4+ T cells and antibody responses to the tumor rejection, FVB mice were depleted of CD4+ T cells during the course of study." (PMID 24324806, 2013). "A previous study from this laboratory showed 125I implantation stimulates the anti-tumor immune response in HCC patients by increasing CD3+ and CD4+ immunocytes and promoting Th2/Th1 deviation." (PMID 23468980, 2013). "We further investigated both CD4 and CD8 T cells from the spleen for their ability to secrete antigen-induced inhibitory cytokines such as IL10 and TGF-β in C3 tumor challenge model." (PMID 23533812, 2013).
tumor (continued). "It is also shown here that vaccination of mice with recombinant yeast-brachyury can elicit brachyury-specific CD4+ and CD8+ T-cell responses capable of reducing tumor burden in an experimental model of metastasis." (PMID 24125763, 2013). "The prevalence of CD4+ Thigh/CD8+ Thigh/%Treglow and the ratio of the percentage of GATA-3+/T-bet+ TILs in the tumor stroma were found to be independent predictive factors of overall survival after surgery in PDAC patients." (PMID 23950747, 2013). "Efficient anti-tumor responses are believed to require CD8+ cytotoxic (killer) T cells, but recent data indicate that induction of CD4+ T helper cells also contribute to clinical efficacy." (PMID 24348481, 2013). "M2 polarization prevents the production of cytokines required to support tumor-specific CD8+ T cells, and CD4+ T helper 1 (Th1) and promotes the function of CD4+ regulatory T cells, and are therefore tumor supportive." (PMID 23983766, 2013). "Our results confirmed that ultra low doses of RFA induce modulation of immune-relevant molecules within the tumor, resulting in a cascade of CEA-specific CD4+ T-cell immune responses." (PMID 23894654, 2013). "We have shown that MMP-2 can directly modulate innate and adaptive immune responses toward melanoma by not only being recognized by specific CD4+ and CD8+ tumor-infiltrating T cells, but also by modulating DC function to polarize TH2 responses." (PMID 24339825, 2013). "Unlike ELISPOT results, CE-vaccinated group had significantly lower IFN-γ-secreting CD8 and CD4 T cells compared to DPX-0907 vaccinated, tumor bearing mice." (PMID 23533812, 2013). "Although we found a very potent and rapid CD4+ T-cell response (production of cytokines and cytotoxins), these cells had only a minor effect on FBL-3 tumor rejection." (PMID 22890822, 2013). "After LF-MF exposure, the proportions of CD3+, CD3 + CD4+ and CD3 + CD8+ T cells in tumor-bearing mice were increased to 24.0%, 13.28% and 7.46%, respectively." (PMID 24314291, 2013). "Specifically, TGF-β plays a central role in the generation and function of CD4+CD25+ Treg and suppression of IFN-γ production by Th1 and CD8+ T cells, finally impeding a successful immune response and favouring tumor progression." (PMID 23861693, 2013). "All responding mice showed significant reduction in myeloid-derived suppressor cells (MDSCs) and an increase in CD4+ and CD8+ T cells in the tumor infiltrates, as well as significant reduction in regulatory T cells (Treg) at the level of draining lymph nodes." (PMID 24156020, 2013). "Strategies that target antigen presentation on both MHC-I and II molecules are ideal as both CD4+ and CD8+ T cells are required to launch potent protective anti-tumor immune response." (PMID 24339825, 2013). "Second, intratumoral CD4+ T cells were shown to recruit CD8+ T cells, enhance their proliferation, survival, and cytolytic function within the tumor microenvironment." (PMID 24066030, 2013). "This resulted in specific elimination of CD4+CD25hiFoxp3+ Treg within brain-infiltrating lymphocytes and complete protection against subsequent orthotopic GL261 tumor challenge." (PMID 23710206, 2013). "The selective depletion of CD4+ or CD8+ T cells led to a marked elevation in tumor volume compared with normal IgG-treated mice (P<0.01), suggesting that RdB/IL23/p35 induces both CD4+ and CD8+ T cells-mediated antitumor immune response." (PMID 23844018, 2013). "Mannosylated dendrimer OVA stimulated CD4+ and CD8+ T-cell responses and antibodies and protected mice against a OVA+ tumor challenge." (PMID 24228179, 2013). "TDE mediated DC maturation and antigen presentation (MHC-II and ICAM) propagates T cell stimulation, demonstrated by increased CD4+ and CD8+ T-cell proliferation, the induction of enhanced CTL based tumor cell lysis and the generation of Th1-type memory." (PMID 24376443, 2013).
tumor (continued). "Activated tumor-infiltrating Tregs were found to express higher levels of CTLA-4, GITR and PD-1, which were observed in the Tim-3+Foxp3+ CD4 T cells." (PMID 23526963, 2013). "When the tumours were analysed via flow cytometry, tumours formed by S12.5 cells contained larger populations of CD45+CD4+ cells and CD45+CD8+ cells (28.8% and 17.3% respectively), compared with tumours formed by SCCVII cells." (PMID 24251770, 2013). "For integrins, Th1 CD4 T cells showed a higher expression of VLA-4 and VLA-6 (α6β1 integrin) than Th2 cells, and the Th1 cells displayed preferential tumour homing and therapeutic effect in a subcutaneous melanoma model." (PMID 23717511, 2013). "Administration of CD4 T cells, and in particular Th1 cells, has been shown to prevent exhaustion of CD8 T cells, enhance tumor infiltration of CD8 T cells and result in effective tumor eradication." (PMID 24265631, 2013). "All tumours contained CD25+ cells, which probably represent regulatory CD4+ (or CD8+) T cells involved in peripheral tolerance to self-antigens." (PMID 23132370, 2013). "Spleens were harvested from vaccinated animals, CD4+ and CD8+ T cells were isolated and stimulated with D5LacZ tumor cells in IFN-γ ELISPOT assays." (PMID 23768240, 2013). "Consistent with this, we observed elevated numbers of both CD4+ and CD8+ cells in tumours initially formed by S12.5 cells as compared with tumours that developed in mice injected parental SCCVII cells." (PMID 24251770, 2013). "We also investigated the role of antigen specificity of the CD4 T cells by using co-transfer of OVA-specific OTII Th1 or Th2 CD4 cells, together with tumour antigen-specific P14 CD8 T cells." (PMID 23717511, 2013). "In this light, MDSC-derived TGFβ not only suppresses cytolytic activity of T lymphocytes, but it has also been demonstrated in the B16 murine melanoma model to promote expansion of CD4+ CD25+ FOXP3+ Tregs in both tumors and tumor-draining lymph nodes." (PMID 23874338, 2013). "We sorted CD4+ CD25+ (Treg) and CD4+ CD25− (conventional T) T cell subsets from the spleen from PBS- or BLM-treated tumor-bearing mice, and tested their capacity to blunt IFNγ production by OT-I cells in an in vitro assay." (PMID 23762310, 2013). "Coincident with the anti-tumor response, local elaboration of SLC within the tumor bed elicited a heavy infiltration of CD4+, CD8+T cells and CD11c+ dendritic cells into the tumor sites." (PMID 24078089, 2013). "MDSC can abrogate the expression of L-selectin (CD62L) on both CD4+ and CD8+ T cells, subverting the homing of these cells to the tumor site leading towards a dominant immunosuppressive microenvironment." (PMID 23394575, 2013). "Finally, transfer of only CD4 T cells may be desirable as they can mediate strong anti-tumor effects and potential for helping endogenous immune responses, but CD4 T cells may not exhibit the CD8-dependent cross reactivities that the same TCRs mediate in CD8 T cells." (PMID 23970885, 2013). "Vaccination with MHC class I/II-loaded DCs has been shown to both increase the frequency of tumor-specific CD8+ T cells and co-activate CD4+ T cells, thereby further improving clinical responses." (PMID 24348481, 2013). "While the CD4 T cell helper type 1 (TH1) is crucial in promoting an effective cellular immune response and as such beneficial in an anti-tumor response, the TH2 phenotype is on the contrary promoting a humoral immune response." (PMID 23949004, 2013). "Since antigen presentation to CD4 T cells is less stringent than cross-presentation to CD8 T cells, this function is likely to be readily achieved by APC present in the tumour bearing mouse brain." (PMID 23717511, 2013). "This strategy has been shown to effectively elicit a potent CD4+ and CD8+ T cell response in mouse tumor models." (PMID 23606870, 2013).
tumor (continued). "We found that these mice had enhanced levels of both CD4+ and CD8+ effector memory and central memory T cells in the tumor-draining lymph nodes, correlating with protective immunity to a rechallenge with tumor cells." (PMID 23626745, 2013). "Expansion of naïve transgenic OVA specific CD4+ T cells and hemagglutinin specific CD8+ T cells is inhibited by murine tumor-induced MDSC or regulatory DC via arginase." (PMID 23717444, 2013). "After 8 cycles of NAC, there was a significantly reduced % of CD4+CD25+CD127- FOXP3+Tregs, compared with pre-treatment levels, in patients who had a good pathological response in their tumours (Group I and II) (p = 0.033)." (PMID 23320561, 2013). "It has been demonstrated that effector CD4+ T cells promoted CTL survival and tumor localization via rendering tumor environment permissive in the course of adoptive CTL therapy." (PMID 23785406, 2013). "It has also been reported that CTX pretreatment can remodel the local immune profile with increased IFN-γ-producing CD4+ and CD8+ effector T cells and decreased Treg cells in tumor microenvironment." (PMID 23941509, 2013). "The main goal of cancer vaccines is to elicit a tumor-specific adaptive immune response by activating CD8+ cytotoxic T lymphocytes for tumor cell lysis and Th1 CD4+ T cells to enhance CTL activity." (PMID 24967094, 2013). "In man, Tregs (CD4+ CD25+ FOXP3+ (Forkhead Box Protein 3)) have been documented in blood, lymph nodes, ascites and infiltrating the tumour microenvironment in a variety of solid cancers." (PMID 23320561, 2013). "This combination of both high CD8 and CD4 effector to Treg and MDSC ratios in peritoneal cavity represents the shift of the normally suppressive tumor melieu to a more stimulatory state which is more permissive for immune mediated tumor destruction." (PMID 24044888, 2013). "Tumor infiltrating cells were analyzed by flow cytometry following staining with antibodies to CD8, CD4, and FoxP3." (PMID 23935927, 2013). "Our isolation protocol data indicated that among tumor-infiltrating cells, 4.16 ± 0.12% were GFP-positive cells, 14.2 ± 0.34% were CD4+ cells, and 2.05 ± 0.23% were CD11c+ DCs." (PMID 24040017, 2013). "Taken together, CD4 T cells, CD8 T cells, and NK cells were essential for the anti-tumor immunity generated by the E6 and E7 fusion protein vaccines." (PMID 24058440, 2013). "During this priming phase by the tumor, CD8+ T cells are instructed by CD4+ T cells to generate memory recall responses, and as such their elimination one day before vaccination has a null effect on the generation of recall responses." (PMID 24066030, 2013). "The effects of MF on innate and adaptive immune parameters, including macrophage, dendritic cell, CD4+ T and CD8+ T lymphocytes in tumor-bearing mice were analyzed." (PMID 24278103, 2013). "We demonstrate that human dendritic cells treated with recombinant yeast-brachyury can activate and expand brachyury-specific CD4+ and CD8+ T cells in vitro that, in turn, can effectively lyse human tumor cells expressing the brachyury protein." (PMID 24125763, 2013). "For example, a high number of CD4+CD25++Foxp3+ regulatory T-cells (Foxp3+Tregs) have been observed in the peripheral blood and tumor microenvironment of cancer patients." (PMID 23725550, 2013). "Several important techniques are already in use to check for cross-reactivity, including in vitro screening of CD4 and CD8 T cells transduced with tumor-specific TCRs, using as antigen-presenting cells various lines derived from normal tissues." (PMID 23970885, 2013). "CD3+, CD4+, CD8+ T-lymphocyte percentage and CD4+/CD8+ ratio were closely related to the cellular immune function and postoperative anti-tumor immunity." (PMID 23575450, 2013). "Active Tregs inhibit activation of CD4+, CD8+ T cells and B cells, which can finally result in the resistance of immune cells to tumor antigens." (PMID 24350772, 2013).
tumor (continued). "We propose that effector CD4+ T cells, which are largely regulated by Foxp3+ Tregs during tumor formation, are capable of maintaining immune control against FBL-3 tumor via direct killing and can functionally replace CD8+ T cells." (PMID 22890822, 2013). "Evidence suggests that both CD4+ and CD8+ effector cells can participate in the effector phase of the anti-tumor immune response." (PMID 24829752, 2013). "Tumor cells (MCF-7/HBL-100) were then co-incubated with unprimed- and placebo-/calcarea carbonica-primed CD4+ and CD8+ T cells for 48 hrs." (PMID 24053127, 2013). "In DT-treated mice, significantly more CD4+CD154+ T cells expressed the cytokines IFN-γ, TNF-α, and IL-2 than in mice receiving only tumor cells." (PMID 22890822, 2013). "Early lesions contain a large proportion of non-malignant cells, which primarily consist of dendritic cells, macrophages and tumor-infiltrating cytotoxic CD8 and CD4 T cells." (PMID 23949004, 2013). "In as study with glioma patients, who were vaccinated with autologous tumor-lysate-loaded DCs after RT-TMZ therapy, increased frequency of interferon-gamma-positive CD4+ T cells was observed." (PMID 23133490, 2012). "Tumor survival and growth in immunocompetent mice correlated with T lymphocyte levels involved in cell immunity; fewer CD3+, CD3+CD4+ T cells in peripheral blood from obese than lean mice led to tumors growing larger and faster in obese relative to lean mice." (PMID 23170114, 2012). "Similarly, these same CD4+Foxp3+CD25low Tregs derived from vaccinated Foxp3GFP neu-N mice suppressed high avidity T cell IFNγ secretion in vivo after they were transferred into tumor bearing FVB/N mice treated with the 3T3neuGM vaccine and high avidity T cells." (PMID 22359647, 2012). "DC capture and process tumor antigens and cross-present MHC class II-restricted antigens to CD4 T cells." (PMID 22400038, 2012). "To test the involvement of T cells in the observed anti-tumour response in AIRE−/− mice, we measured frequencies of activated CD4+ and CD8+ T cells following tumour challenge in lymph nodes (LN)." (PMID 22506061, 2012). "Regulatory T cells (CD4+CD25+FoxP3+; Tregs) do not only inhibit autoreactive T cells to maintain immunological self-tolerance, but also anti-tumor immune responses in the tumor microenvironment." (PMID 22674057, 2012). "The immunization resulted in infiltration of more T cells (as identified by CD3 staining), including both CD4+ and CD8+ T cells in tumor tissues harvested from DCLV-PSCA-immunized mice, than that of DCLV-Null-treated mice." (PMID 23139820, 2012). "We also visualized CD4+ and CD8+ T cells as well as Treg in tumor and unaffected mucosa in situ using immunofluorescence." (PMID 22319577, 2012). "The effect was most frequently noticed when infiltrating CD4+ and CD8+ T cells were present around degenerated tumor cells of the irradiated primary tumor." (PMID 22848871, 2012). "Alternatively, anti-CD4 Ab used to deplete CD4+ T cells will also eliminate CD4+CD25+Foxp3+ Treg cells, which have been shown to play a critical role in tumor-mediated tolerance of Teff cells." (PMID 23144888, 2012). "The increase in the flow of CD4 and CD8 cells to the tumor site after beginning of Vemurafenib administration further supports combinatorial strategies." (PMID 22924051, 2012). "From our data we conclude that both CD4 and CD8 T cells of the immune system are contributing to tumour rejection by the autoreactive immune repertoire." (PMID 22506061, 2012). "CD4+FOXP3− cells from both unaffected colonic tissue and tumors had a lower demethylation than the CD4+FOXP3+ cells (range 51–100% and 53–74% in the tumor and unaffected tissue, respectively)." (PMID 22319577, 2012). "Our finding agrees with other studies that show that with sufficient CD4+ T cell help, low avidity CD8+ T cells can become active and infiltrate the tumor microenvironment." (PMID 22359647, 2012).